CFAP70 (cilia and flagella associated protein 70)
Description:
Axoneme-binding protein that plays a role in the regulation of ciliary motility and cilium length. Essential for the assembly of the sperm flagellum and the correct shaping of the sperm head, during spermiogenesis.Contributes in part to flagellar biogenesis by stabilizing QRICH2, promoting the cytoplasmic preassembly of CFAP61 and CFAP91, and regulating the manchette localization of axoneme-associated proteins such as IFT88, DNAI1 and CFAP61.
Synonyms: TTC18; FLJ25765; SPGF41
Tractability: PROTAC: ubiquitination databases record sites on it.
Gene: Protein-coding gene on chromosome 10 (73,253,762 to 73,358,864, reverse strand). Ensembl gene ENSG00000156042.
Subcellular location: Cell projection, cilium, flagellum; Cytoplasm, cytoskeleton, flagellum basal body; Cell projection, cilium; Cytoplasm, cytoskeleton, cilium axoneme; Cytoplasm, cytoskeleton, flagellum axoneme
Subcellular location (Human Protein Atlas): Basal body; Centrosome; Cytosol; End piece; Mid piece; Principal piece
Gene Ontology:
Biological process: cilium assembly; cilium movement
Cellular component: ciliary basal body; extracellular exosome; outer dynein arm; sperm flagellum; axoneme; motile cilium; cilium
Genetic constraint (gnomAD): Loss-of-function variants: 71 observed, 115.39 expected, observed/expected ratio (o/e) 0.62, 90% interval 0.51 to 0.75. The upper end of that interval is the gene's LOEUF score, 0.75, which puts it in group 3 of 6, group 1 being the genes least tolerant of losing a copy. Missense variants: 910 observed, 1,169.7 expected, observed/expected ratio (o/e) 0.78, 90% interval 0.74 to 0.82. Synonymous variants: 359 observed, 408.6 expected, observed/expected ratio (o/e) 0.88, 90% interval 0.81 to 0.96.
Homologues: Orthologues: chimpanzee CFAP70 (99% identical), macaque CFAP70 (98% identical), dog CFAP70 (88% identical), pig CFAP70 (88% identical), rabbit CFAP70 (88% identical), rat Cfap70 (82% identical), mouse Cfap70 (82% identical), guinea pig CFAP70 (80% identical), tropical clawed frog cfap70 (55% identical), zebrafish cfap70 (45% identical). Paralogues in human: TTC6 (13% identical), TTC13 (12% identical), TTC34 (11% identical), TTC7A (11% identical), TTC7B (11% identical), OGT (10% identical), TMTC2 (10% identical), TMTC1 (10% identical), TMTC3 (9% identical), BBS4 (8% identical), IFT88 (8% identical), TMTC4 (8% identical), and 2 more.
Diseases named in the same sentence as CFAP70 in open-access papers:
CFAP70 is named in the same sentence as 7 diseases in open-access papers, as found by Europe PMC text mining. Sharing a sentence is not in itself a finding about the gene and the disease. The quoted sentences say what the papers report.
male infertility (3 papers, 2022 to 2025). The inability of the male to effect fertilization of an ovum after a specified period of unprotected intercourse. "For example, the gene CFAP70 (cilia- and flagella-associated protein 70) has been shown to be associated with motile cilia and flagella, and its mutations can lead to male infertility." (PMID 38891632, 2024). "Therefore, we hypothesize that the significant downregulation of DEGs (CFAP70, TTC29, CCDC40, DNAAF4, SYCE3, STK36, SPI1 and EMX2) in hybrid yellow catfish is the primary cause of male infertility or reduced fertility." (PMID 38891632, 2024).
ciliopathy (1 paper, 2018). A genetic disorder of the cellular cilia or the cilia anchoring structures, the basal bodies, or of ciliary function. "Among the list of genes, Cfap70 (or Ttc18) caught our attention as the expression levels appeared to be correlated with the ciliary number, just like Ttc21a (Ift139a) as well as Ttc25, which was recently reported as a novel ciliopathy gene." (PMID 30158508, 2018).
Cirrhosis (1 paper, 2021). A chronic disorder of the liver in which liver tissue becomes scarred and is partially replaced by regenerative nodules and fibrotic tissue resulting in loss of liver function. "The expression of CFAP70 was much lower in pathological than in healthy situations, and this may be due to cirrhosis reducing the sexual function of the patient." (PMID 34877354, 2021).
Infertility (1 paper, 2021). "It has been shown that CFAP70 mutations can cause infertility in previous study." (PMID 34877354, 2021).
tumor (1 paper, 2023). "Using Spearman's rank correlation analysis, we explored the existence of a correlation between anti‐FIRΔexon2, anti‐CFAP70, anti‐KARS, anti‐SNX15, or anti‐SOHLH1 Abs and clinically used tumor markers." (PMID 37964630, 2023).
CFAP70 also shares sentences with these, for which no sentence is quoted: Hydrocephalus (1 paper); primary ciliary dyskinesia (1).